MALAT1 (metastasis associated lung adenocarcinoma transcript 1)
Diseases named in the same sentence as MALAT1 in open-access papers (continued):
Sharing a sentence is not in itself a finding about the gene and the disease.
ovarian carcinoma (continued). "The Akt protein expression level was higher than its phosphorylated form, confirming that the total protein level was not affected; meanwhile, p-Akt was significantly reduced, indicating that MALAT-1 silencing modulated EMT by downregulating the PI3K/Akt signaling pathway in ovarian cancer." (PMID 38201661, 2024). "MALAT1 may play a role in the metastasis of epithelial ovarian cancer cells, but its mechanism needs to be further studied." (PMID 35103065, 2022). "Moreover, MALAT1 upregulation increased paclitaxel resistance of ovarian cancer cells in the tumor microenvironment." (PMID 36105363, 2022). "Furthermore, it was reported that MALAT1 sponges miR-1271-5p and facilitates multiple myeloma and ovarian cancer progression by regulating SOX13 and E2F5, respectively." (PMID 35320950, 2022). "In patients with ovarian cancer, high levels of MALAT1 expression in localized lesions or in serum exosomes may indicate a poor prognosis." (PMID 36419933, 2022). "In addition to diagnosis, exosomal lncRNAs also find application in tumor prognosis, such as lncRNA MALAT1 in epithelial ovarian cancer (EOVAC) and lncRNA MALAT1, PCAT-1 in BC." (PMID 35303879, 2022). "In addition, miR-506 was downregulated in ovarian cancer tissues and cell lines and negatively correlated with MALAT1 expression." (PMID 34204094, 2021). "Other reports have also indicated that MALAT1 regulates the migration and invasion of ovarian cancer cells through controlling the expression of extracellular matrix genes and cell signaling pathways such as phosphoinositide 3-kinase (PI3K)/AKT and Wnt/β-catenin." (PMID 34681900, 2021). "MALAT-1 facilitated epithelial ovarian cancer development through sponging miR-22." (PMID 34207450, 2021). "In cisplatin‐resistant ovarian cancer tissues and cells, MALAT1 was reported to be increased and knock‐down of which could decrease cisplatin resistance." (PMID 34164906, 2021). "We aimed to observe the impact of ginkgolic acid (GA) on the proliferation and metastasis ability of ovarian cancer (OCa) cells and to further explore whether GA affects the malignant progress of OCa via regulating the lncRNA MALAT1/JAK2 axis." (PMID 34987594, 2021). "In ovarian cancer,MALAT1 was reported to facilitate cell proliferationand metastasis." (PMID 31863664, 2020). "In ovarian cancer, a study suggested that MALAT1-miRNA-211-5p may act as a key mediator in the prevention of this disease." (PMID 32993558, 2020). "Exosomal MALAT1 predicts poor prognosis and accelerates angiogenesis in epithelial ovarian cancer." (PMID 33006432, 2020). "In ovarian cancer, a crosstalk between epithelial ovarian cancer cells (EOCs) and endothelial cells may facilitate angiogenesis as EOCs release exosomes including MALAT-1." (PMID 32992718, 2020). "In oesophageal cancer, MALAT1 promotes epithelial-to-mesenchymal transition, while in lung and ovarian cancer, it might confer resistance to pharmacological treatment." (PMID 33375130, 2020). "In ovarian cancer, caspase 3/7 assay showed that MALAT1 knockdown resulted in increased anoikis." (PMID 31744046, 2019). "Recently, a study demonstrated that MALAT1 could sponge miR-211 as a competing endogenous RNA to suppress tumor growth and progression in ovarian carcinoma." (PMID 31143769, 2019). "Via the MAPK pathway, MALAT1 promotes ovarian cancer cell proliferation and migration." (PMID 31379598, 2019). "MALAT1 was significantly overexpressed in the study cohort compared to the normal controls, which is consistent with recent studies linking MALAT1 overexpression with significantly increased cell proliferation and invasion in ovarian cancer." (PMID 30416686, 2018). "MALAT1 promoted ovarian cancer cell proliferation and invasion via activating MAPK pathways." (PMID 29921308, 2018).
ovarian carcinoma (continued). "Metastasis-associated lung adenocarcinoma transcript 1 (MALAT1), associated with the metastasis of lung tumors, promotes the proliferation, migration and invasion of several tumor cells, such as hepatocellular, ovarian cancer, andgastriccancer." (PMID 29435112, 2018). "Furthermore, MALAT1 inhibition markedly suppresses tumorigenicity in SKOV3 ovarian cancer cells and changes the expression of several genes that are involved in cell proliferation, metastasis and apoptosis." (PMID 28637507, 2017). "Nonetheless, based on our current data, we hypothesize that the efficacy of MALAT-1 in promoting ovarian cancer progression could be mediated by up-regulation of MMP13 and down-regulation of MMP19 and ADAMTS1." (PMID 27227769, 2016). "miR-503-5p is an inhibitory effector in ovarian cancer that could be sponged by MALAT1." (PMID 35046387, 2022). "Besides, MALAT1 could regulate ovarian cancer progression and DDP- resistance by miR-1271-5p/E2F5 Axis." (PMID 34512721, 2021). "Thus, our data suggests that overexpression of MALAT-1 might promote ovarian cancer progression by regulating the expression of MMP19, ADAMTS1 and MMP13 genes." (PMID 27227769, 2016). "H19 and MALAT1 may play a suppressive role in ovarian cancer metastasis." (PMID 24379988, 2013). "In epithelial ovarian cancer (EOC), METTL16 negatively correlates with lncRNA MALAT1, and their interaction up-regulates β-catenin, thereby inhibiting the growth, migration, and invasion of EOC cells." (PMID 41256854, 2025). "Several lncRNAs like ZFAS1, MALAT1, H19 have been shown to increase resistance to cisplatin while lncRNA like GAS5, NEAT1 lower cisplatin resistance in ovarian cancer cells." (PMID 39912983, 2025). "A prognostic signature with eleven lncRNAs, including NEAT1, HOTAIR, MALAT1, ANRIL, CCAT2, ZFAS1, UCA1 have been shown to predict poor patient survival and outcome in ovarian cancer patients." (PMID 39912983, 2025). "In ovarian cancer, the lncRNAs are over (e.g. HOTAIR, MALAT1)—or under (e.g. TUB4B, GAS5) – expressed and have been assocated with tumor growth, metastasis, angiogenesis, and drug resistance." (PMID 38796525, 2024). "Other exosomal nucleic acids including circRNAs, such as Circ-0001068 and CircFoxp1; lncRNAs, such as MALAT1 and UCA1; and mitochondrial DNA (mtDNA) demonstrate potential as biomarkers for the early detection of ovarian cancer." (PMID 38796525, 2024). "MALAT1 elevated the expression of IL-1β, p-P38, p-NF-κB, COX2 and PGE2 signaling, and reduced caspase-3 level and promoted Bcl-2 expression in ovarian cancer cells." (PMID 36105363, 2022). "Overexpression of lncRNA MALAT1 led to promotion of cyclin D1, pAkt and p-PI3K, contributing to acceleration of ovarian cancer cell proliferation." (PMID 36105363, 2022). "Among others, lncRNA HOTAIR, H19, MALAT1, and HOST2 can be used as potential therapeutic targets for ovarian cancer and are closely related to tumorigenesis and metastasis in ovarian cancer." (PMID 35706412, 2022). "In fact, MALAT1 was found to sponge miR‐22 thus counteracting its inhibitory effect on c‐myc and c‐myc‐mediated EMT process in ovarian cancer." (PMID 34164906, 2021). "Upregulation of metastasis-associated lung adenocarcinoma transcript 1 (MALAT1, also known as nuclear-enriched abundant transcript 2 (NEAT2) or LINC00047) was found in various solid tumors, including epithelial ovarian cancer (EOC)." (PMID 34638541, 2021). "By sponging miR-211, MALAT1 up-regulates PHF19 expression and induces RBFOX2 expression and alternative processing of the tumor suppressor gene KIF1B, leading to ovarian cancer cell proliferation, invasion, increased anoikis, and anchorage-independent growth." (PMID 32174966, 2020). "In ovarian cancer cells, MALAT1 sponges miR-211, thus up-regulating PHF19 expression and facilitating ovarian cancer progression." (PMID 32174966, 2020). "Among these LncRNAs, MALAT1 and SNHG14 have been demonstrated to function as oncogenes in ovarian cancer." (PMID 31794425, 2019).
ovarian carcinoma (continued). "Additional studies on the effects of NEAT1, MALAT1 and MEG3 aberrant expression in CCs should bring critical insights into their function during oocyte maturation and in ovarian carcinoma." (PMID 29396444, 2018). "In this study, we measured MALAT-1 expression levels in primary normal ovary and ovarian tumor tissues and investigated the biological role of MALAT-1 in ovarian cancer pathogenesis." (PMID 27227769, 2016). "In summary, METTL16 acts as a key regulator of OV progression through modulation of MALAT1 and β-catenin signaling, and targeting the METTL16–MAT2A axis may represent a promising therapeutic strategy for ovarian cancer." (PMID 41322419, 2025). "In ovarian cancer, it has been shown that the lncRNAs HOTAIR, MALAT1, LINC01127, AB073614, ElncRNA1 and ANRIL modulate the PI3K pathways, while LncRNA HOST2 GAS5, TUBA4B modulate the RAS pathway and lncRNAs TUG1, HOXD-AS1, SNHG20 and EBIC modulate the Wnt/β-catenin pathway." (PMID 39912983, 2025). "MALAT-1 knockdown inhibited cell growth and metastasis by inhibiting EMT in ovarian cancer." (PMID 38201661, 2024). "Moreover, HOTAIR is shown to be not only overexpressed in BC but also in ovarian cancer; thus, suggesting that HOTAIR and MALAT1 are oncogenic lncRNAs." (PMID 36387279, 2022). "MALAT1 upregulation also elevated the expression of ZEB2, YAP, vimentin and decreased E-cadherin, suggesting that MALAT1 triggered EMT and tumor metastasis in ovarian cancer cells." (PMID 36105363, 2022). "Similarly, silencing MALAT1 restricted the EMT process and metastasis of ovarian cancer cells via PI3K/Akt pathway inhibition." (PMID 34288373, 2021). "Moreover, MALAT1, NEAT1, GAS5, H19 and XIST have been experimentally validated to be ovarian cancer-related lncRNAs, which were identified as hubs that connect 26, 15, 22, 20 and 9 modules in OV dataset, respectively." (PMID 30732558, 2019). "To date, there is no report implicating MALAT-1 in the regulation of MMPs or ADAMTS1 expression in ovarian cancer." (PMID 27227769, 2016). "MALAT-1 promotes the growth and migration of ovarian cancer cells, suggesting that MALAT-1 may be an important contributor to ovarian cancer development." (PMID 27227769, 2016). "Notably, and in contrast to prior reports in ovarian cancer, no such relationship was observed for MALAT1." (PMID 31745703, 2020). "Suppression of MALAT-1 resulted in downregulating the expression of MMP13 and up-regulating the expression of MMP19 and ADAMTS1 genes, indicating that MALAT-1 may involved in ovarian cancer by regulating the expression of the MMP13, MMP19, and ADAMTS1 genes." (PMID 27227769, 2016). "Studies have shown that METTL16 is significantly downregulated in epithelial ovarian cancer (EOC) tissues and cells, whereas its target lncRNA MALAT1 is highly expressed, exhibiting a negative correlation." (PMID 41322419, 2025). "Indeed, MALAT1 has been reported to be overexpressed in SKOV3ip ovarian cancer cells, a cell line derived from SKOV3 and harboring a more metastatic phenotype, but the functional implication of MALAT1 overexpression has not yet been investigated." (PMID 26992233, 2016).
pancreatic cancer (83 papers, 2013 to 2026). "Detection of MALAT1 in pancreatic tissue is a diagnostic biomarker with 66% sensitivity and 72% specificity for pancreatic cancer." (PMID 38559560, 2024). "The diagnostic and prognostic effects of MALAT1 in patients with pancreatic cancer have been evaluated by Gene Expression Omnibus, Oncomine, and The Cancer Genome Atlas databases." (PMID 36452326, 2022). "One example of a ncRNA which plays a role in canonical network is the highly abundant lncRNA metastasis-associated lung adenocarcinoma transcript 1 (MALAT1), which is overexpressed in lung, breast, and pancreatic cancers, etc.." (PMID 34069428, 2021). "Further, we chose the highly expressed lncRNA MALAT1 (metastasis associated lung adenocarcinoma transcript 1) for staining in colorectal, breast and pancreatic cancer." (PMID 30189670, 2018). "By interrogating Gene Expression Omnibus, Oncomine, and The Cancer Genome Atlas databases, authors found MALAT1 significantly elevated in patients with pancreatic cancer, and ROC curves showed a moderate diagnostic power of MALAT1 expression." (PMID 29739426, 2018). "In conclusion, our study suggested that PVT1, HOTTIP, MALAT1 was associated with the efficacy of first-line treatment with GEM based chemotherapy in pancreatic cancer." (PMID 29221115, 2017). "The lncRNA MALAT-1 (metastasis-associated lung adenocarcinoma transcript 1) was found to be upregulated in CSCs, and high expression levels of this lncRNA positively correlated with the proportion of CSCs in pancreatic cancer cells." (PMID 26880946, 2016). "Interestingly, genes associated with pancreatic cancer such as MALAT1 (noncoding RNA), CTRB2 (serine protease), CST7 (cysteine peptidase inhibitor), and BTG1 (anti-proliferation factor) were picked in multiple topics." (PMID 36968070, 2023). "Moreover, Atg4, Beclin-1, and, P62 can influence EMT and contribute to CSC maintenance in breast cancer, while in pancreatic cancer, lncRNA MALAT-1, can promote EMT and CSC-associated proteins." (PMID 33799834, 2021). "lncRNA MALAT-1 is also associated with chemoresistance of pancreatic cancer." (PMID 34439315, 2021). "Similarly, an interaction between long-noncoding RNA metastasis-associated lung adenocarcinoma transcript 1 (MALAT-1) and miR-200c-3p was reported in pancreatic cancer." (PMID 34439151, 2021). "Although loss of MALAT-1 decreased pancreatic tumor growth and metastasis in a mouse orthotopic model, the loss of MALAT-1 in highly aggressive p53L/L;LSL-KrasG12DL/+;p48Cre+/- and the p53L/+ heterozygotes only slightly increased survival time in the p53L/+ heterozygotes." (PMID 29389953, 2018). "To investigate whether MALAT1 is associated with pancreatic cancer progression further, we analysed the effects of MALAT1 knockdown on pancreatic cancer cell migration and invasion." (PMID 28701723, 2017). "Moreover, eight lncRNAs were also verified, including metastasis associated lung adenocarcinoma transcript 1 (Malat1), a lncRNA recently shown to promote pancreatic cancer cell proliferation." (PMID 28747214, 2017). "Previous studies also claimed that increased Malat1 expression was positively correlated with poor prognosis in pancreatic cancer and PCa." (PMID 38501046, 2024). "They showed that lncRNA MALAT1 was upregulated in 15 pancreatic cancer tissues compared to the adjacent tissues." (PMID 38226210, 2024).
pancreatic cancer (continued). "bPNAs, on the other hand, show a slightly better displacement capability, with EC50 values ranging between 0.2 and 9 μM, albeit with a comparable reduction in the MALAT1 expression levels of bPNA-treated pancreatic cancer cells." (PMID 38338910, 2024). "MALAT-1 has increased in many types of cancers, including pancreatic cancer and pancreatic cell lines." (PMID 38559560, 2024). "A bPNA targeting the SL region of the MALAT1 triple helix showed an almost 50% reduction of MALAT1 in pancreatic cancer cells." (PMID 38338910, 2024). "Recently, MALAT1 was identified to govern pancreatic cancer progression via modulation of miR-129-5p." (PMID 36212476, 2022). "MALAT1 downregulation retarded pancreatic cancer progression via targeting Hippo-YAP signaling pathway." (PMID 36212476, 2022). "We also performed multivariate Cox regression analysis on prognosis-related cuproptosis lncRNAs and found that five lncRNAs, AC025257.1, TRAM2-AS1, AC091057.1, LINC01963, and MALAT1, exhibited significant prognostic value for pancreatic cancer." (PMID 36406148, 2022). "We found that shMALAT1 transfection suppressed the expression of lncRNA MALAT1, while MALAT1 cDNA transfection elevated the expression of MALAT1 in pancreatic cancer cells." (PMID 36212476, 2022). "In the current study, we found that depletion of MALAT1 reduced cell viability, whereas overexpression of MALAT1 enhanced viability of pancreatic cancer cells." (PMID 36212476, 2022). "LncRNA MALAT1 has been found to maintain the cancer stem cell-like properties in pancreatic cancer cells, including self-renewing ability, chemoresistance and angiogenesis." (PMID 36212476, 2022). "To define the role of lncRNA MALAT1 in regulation of viability of pancreatic cancer cells, we used shMALAT1 or MALAT1 cDNA to modulate the expression of MALAT1 in pancreatic cancer cells." (PMID 36212476, 2022). "Taken together, METTL3 regulates the expression of PD-L1 partly due to regulation of lncRNA MALAT1 in pancreatic cancer." (PMID 36212476, 2022). "LincRNA Malat1 promotes aggressive pancreatic cancer proliferation and metastasis via multiple reported signaling pathways." (PMID 35941362, 2022). "CCND1, MAPK8, VEGFA, FOS, CDH1, and HSP90AA1 have been identified as the target genes of MALAT1 in patients with pancreatic cancer." (PMID 36452326, 2022). "Taken together, lncRNA MALAT1 is involved in METTL3-mediated promotion of PD-L1 expression in pancreatic cancer." (PMID 36212476, 2022). "In the present work, it was confirmed that MALAT1 was positively regulated by IPO7 in pancreatic cancer cells." (PMID 34660566, 2021). "MALAT-1 also transcriptionally regulated Sox-2 expression and enhanced stem cell-like phenotypes in pancreatic cancer cells, suggesting its role in pancreatic stemness and tumorigenesis." (PMID 34439315, 2021). "MALAT1 is also reported to be overexpressed in pancreatic cancer, and MALAT1 knockdown repressed the malignant biological behaviors of pancreatic cancer cells." (PMID 34660566, 2021). "In the present work, our data suggested that IPO7 positively regulated MALAT1 expression in pancreatic cancer." (PMID 34660566, 2021). "In pancreatic cancer, the lncRNA MALAT-1 exerts oncogenic functions via promotion of EMT and stimulation of CSC-associated protein expression suggesting a role for this lncRNA in stimulating stem-like phenotypes." (PMID 33799834, 2021). "Collectively, our results indicated that miR-129-5p was a downstream target of MALAT1 in pancreatic cancer cells." (PMID 34660566, 2021).